PARP1 (poly(ADP-ribose) polymerase 1)
Diseases named in the same sentence as PARP1 in open-access papers (continued):
Sharing a sentence is not in itself a finding about the gene and the disease.
cancer (continued). "Thus, while the findings presented here are potentially only relevant to this singular cancer cell line, we are confident the results accurately reflect the role of PARP1 in human cells." (PMID 30410680, 2018). "In this novel scenario, iCDK4/6-induced PARP1 depletion could sensitize growth arrested cancer cells to cytotoxic agents." (PMID 29306194, 2018). "The absence of PARP1 does cause telomere shortening (albeit indirectly), but the re-expression of PARP1 in these cells only allowed cells to stabilize the longer telomeres that were subsequently generated by the clonal variation in telomerase-positive cancer cells." (PMID 30410680, 2018). "Poor prognosis of cancer patients expressing PARP1-related DDR molecules might be related with their role in DNA damage." (PMID 29784019, 2018). "PARP1 levels are generally higher in cancer cells than in FTE-187 cells." (PMID 29684820, 2018). "Understanding how cells cope with DNA damage and exactly how PARP1 works could help in the fight against cancer." (PMID 30088474, 2018). "A prevailing theory (although other models have been proposed; see for example) is that SSBs, which normally would be recognized for repair by PARP1, can accumulate over time and in a cancer cell such lesions would be converted to DSBs as a consequence of DNA replication." (PMID 30410680, 2018). "Inhibitors for PARP1 have recently been identified and are promising agents for cancer treatment." (PMID 29967475, 2018). "Poly(ADP‐ribose) polymerase 1 (PARP‐1) is a multifunctional protein of importance in cancer." (PMID 30467127, 2018). "In support of this hypothesis, synthetic lethality is induced by pharmacologic inhibition of PARP1/2 in HR-defective cancer cells." (PMID 30274183, 2018). "PARP1 is of special interest because it is a validated target for cancer therapy." (PMID 30088474, 2018). "However, our results point to a potential utility of the anti-cancer drug class of PARP-1 inhibitors in the therapeutic context of primary metabolic traits." (PMID 29392078, 2018). "It was generally believed that when the repair of SSBs was blocked by PARP1 inhibition, SSBs would be converted into DSBs in S-phase that can only be repaired by HRR, therefore impaired HRR, as in cancer cells carrying BRCA1 or BRCA2 mutations, would render synthetic lethality with PARP1 inhibition." (PMID 29684820, 2018). "PARP1 recruits KLF4 to activate telomerase expression in cancer cells." (PMID 29899271, 2018). "Our data suggest that inhibition of PARP-1 as well as TOPO I may sensitize cancer cells to chemotherapeutic agents in certain situations." (PMID 29843366, 2018). "Furthermore, the expression of cleaved caspase-3 and cleaved PARP1 increased in these cancer cells after exposure to YLT-11." (PMID 30337519, 2018). "RB1 deficiency makes cancer cells resistant to CDK4/6 inhibitors, but may also prevent efficient PARP1 gene targeting." (PMID 29306194, 2018). "Hence, PARP1 inhibitors are of particular interest for the treatment of cancers with inherent defects in their DNA repair pathways, such as in BRCA1/2." (PMID 29783721, 2018). "Based on our data and the literature, we envision that EZH2 inhibitors may improve the efficacy of PARP1 inhibitors for new therapeutic approaches, as well as for current cancer treatment, leading to a more precise use of these classes of compounds." (PMID 29535829, 2018). "Since patients often develop resistance to olaparib, our results suggest that PARP1 inhibitors might be combined with EZH2 inhibitors to improve cancer therapy." (PMID 29535829, 2018).
cancer (continued). "Two such agents, the PARP1 inhibitor, olaparib, and the chemotherapeutic agent, gemcitabine, are of particular interest based upon previous studies and known activity in a variety of cancers." (PMID 29783721, 2018). "In addition, PARP1 also regulates necroptosis of cancer cells through extracellular signal-regulated kinases (ERK), and C-jun N-terminal kinase (JNK) pathways." (PMID 28991194, 2017). "The inhibition of PARP-1 activity might be indicative of cancer cell survival with decreased DNA repair." (PMID 28086241, 2017). "In addition, BRCA1/2 mutant cancers were found to be selectively sensitive to inhibition of the poly-(ADP)ribose polymerase PARP1 (refs 7, 8, 9)." (PMID 28714471, 2017). "One mechanism of PARP inhibitor resistance that has been described for other cancer types is the downregulation of PARP1 itself, which we hypothesized directly affects SLFN11 levels." (PMID 28212573, 2017). "PARP1, a nuclear enzyme, has now been identified in both the nucleus and cytoplasm of cancer cells." (PMID 28991194, 2017). "PARP1 also modulates cancer cell cycle via controlling cell death." (PMID 28991194, 2017). "PARP1 hyperactivation is involved in therapeutic resistance in multiple cancers." (PMID 28993682, 2017). "Interestingly, the combination of ATR inhibitor with Olaparib synergistically sensitizes NEIL3 deficient cancer cells, suggesting that blocking the ATR-mediated DNA damage response synergizes the cytotoxicity of PARP1 inhibitor." (PMID 29348879, 2017). "Initially, PARP1 in cancer cells will activate the apoptosis pathway." (PMID 28991194, 2017). "Additionally, SLC6A9 downregulation in resistant cancer cells interfered with PARP-1 activity to influence therapeutic efficacy." (PMID 28086241, 2017). "Interestingly, dePARylated CTCF is associated in a stable protein complex with PARP-1 and NMNAT-1 in cancer cells harboring silenced tumor suppressor genes." (PMID 29029387, 2017). "To explore this hypothesis, we treated a panel of cancer cell lines with HT, cDDP and a PARP1-i and measured various end-point relevant in cancer treatment." (PMID 27557507, 2017). "Notably, however, cancer cells with defects in HR (most commonly arising from mutations of BRCA1 and BRCA2 proteins) have exhibited vastly increased sensitivity to PARP-1 inhibitors." (PMID 28058462, 2017). "Furthermore, 3-AB was shown to weaken cancer cell DNA repair by Western blot analysis of PAR (active product of PARP-1) and γH2AX, as well as by confocal laser scanning imaging." (PMID 28086241, 2017). "In addition, PARP1 also plays key roles in gene transcription, which also contributes to cancer development and progression." (PMID 29212245, 2017). "We introduced SLC6A9 siRNA into cancer cells, and PARP-1 expression was significantly decreased." (PMID 28086241, 2017). "Interestingly, in cancer cells, PARP-1 expression has been reported to be post-transcriptionally regulated by miR-124." (PMID 28828398, 2017). "PARP1 has been found to be overexpressed in various carcinomas." (PMID 28991194, 2017). "Notably, the phosphorylation of γH2AX, which is normally undetectable in the gas control (DMSO), was also detected in the gas control in the presence of AZD2281, which implied the role of PARP1 in the protection of the cancer genome from endogenous DNA damage." (PMID 27145275, 2016). "Poly(ADP-ribose) polymerase inhibitors (PARPIs) kill cancer cells by trapping PARP1 and PARP2." (PMID 27708213, 2016). "There are various PARP-1 inhibitors that are in clinical trial for different kinds of cancers." (PMID 27659937, 2016). "Interestingly, over-expressed PARP1 has been demonstrated in various cancers such as melanomas, glioblastoma and breast cancer." (PMID 28442756, 2016).
cancer (continued). "Therefore, combined use of PARP1 inhibitors and conventional genotoxic cancer therapeutic agents has been suggested for the treatment of malignant tumors." (PMID 27643881, 2016). "For such cancers, PARP-1 inhibitors are emerging as promising monotherapy agents." (PMID 27304949, 2016). "So, PARP-1 inhibition in combination with carbon ion exposure could be a promising tool in hadrontherapy for treatment of cervical or other cancers and could be beneficial in post-irradiation stages by stopping metastasis." (PMID 27659937, 2016). "Therefore, the inhibition of the BER pathway using a PARP1 inhibitor drastically induced the phosphorylation of γH2AX, and was followed by the programmed cell death of cancer cells." (PMID 27145275, 2016). "Therefore, combination of PARP-1 inhibitors with radio- and chemo-therapy to enhance antitumor effects has been an initial focus in cancer treatment." (PMID 27304949, 2016). "Moreover, it has been suggested that the expression of PARP1, γH2AX, BRCA1, and BRCA2 are closely associated with the progression of various human malignant tumors." (PMID 27643881, 2016). "Numerous PARP1-specific inhibitors are available for the clinical treatment of cancer." (PMID 25872931, 2015). "As a result, PARP1 is highly overexpressed in various forms of cancer." (PMID 26337803, 2015). "In addition, high expression level and activity of Parp1 are correlated with pluripotent status, reprogramming, and cancer." (PMID 26184161, 2015). "Thus, PARP-1 seems to play a positive role in the regulation of Snail expression, thereby favoring the survival of cancer cells." (PMID 25938539, 2015). "With this concern, we next examined whether the effect of PARP1 inhibition on cancer growth is mediated through activation of apoptotic process." (PMID 26540566, 2015). "In several types of cancer, the expression of PARP1 is high and, therefore, inhibiting the expression of PARP1 may improve outcomes in patients with cancer." (PMID 25543761, 2015). "PARP-1 promotes tumorigenesis and cancer progression by acting on different molecular pathways." (PMID 26314963, 2015). "Finally, in cancer cells, a switch in the expression from PARP1-regulated macroH2A1.1 to PARP1-insensitive macroH2A1.2 is observed." (PMID 26262644, 2015). "Indeed, this cancer exhibits a wide heterogeneity, and it has been demonstrated that PARP-1 expression levels vary from lower to higher levels, depending on the tumor type." (PMID 25268610, 2014). "In this updated meta-analysis of 43 studies with 17351 cases and 22401 controls, pooled analysis did not yield significant association between PARP1 Val762Ala polymorphism and overall cancer risk." (PMID 24489833, 2014). "Furthermore, it was also demonstrated that PAK4 prevented cancer cells from undergoing apoptotic cell death by inhibiting the activation of caspases-3/8/7 and subsequently leading to PARP1 cleavage." (PMID 25238288, 2014). "Based on the interaction of synthetic lethality that has been described between PARP1 and both BRCA1 and BRCA2, we hypothesize that this and other genes involved in the BER pathway could potentially be associated with cancer risk in BRCA1/2 mutation carriers." (PMID 24698998, 2014). "Therefore, PARP-1 inhibitors have recently found widespread use in the development of novel strategies for cancer treatment, and several PARP-1 inhibitors are currently undergoing phase I/II trials for FDA approval for treatment of tumors." (PMID 24504413, 2014). "Proteolytic cleavage of PARP-1 by the action of EOs might be indicative of modification of the DNA repair process in the cancer cells." (PMID 25003106, 2014). "Currently, several agents capable of inhibiting PARP-1 are under test and those drugs might be useful as chemosensitizers for cancer therapy." (PMID 24797896, 2014). "We hypothesize that SNPs in PARP1 and other members of BER may be associated with cancer risk in BRCA1 and BRCA2 mutation carriers." (PMID 24698998, 2014).
cancer (continued). "In addition, CHD1L activity can be blocked by PARP-1 inhibitors, which have already been explored for use in cancer treatment." (PMID 25153161, 2014). "For this reason, the greatest remaining challenge for the use of PARP-1 inhibitors is to find biomarkers that would indicate whether cancer cells would be sensitive to this type of treatment." (PMID 23405229, 2013). "Interestingly, PARP-1 inhibition seems to be effective in cancers that often show overexpressed ETS proteins, including ovarian, prostate and breast cancers." (PMID 23405229, 2013). "However, further studies should also be pursued to investigate how PARP1 inhibitors change RNA metabolism of cancer cells by influencing RBP activities in the treated tumors." (PMID 23921685, 2013). "Thus, this study provides important insight into optimizing the chemotherapeutic strategies designed to improve the treatment of cancer patients via the targeting of PARP-1 and PARG." (PMID 23254695, 2013). "A transient inhibition of DNA repair using potent PARP1 inhibitors could improve the efficacy of cancer treatments, in fact, PARP1 inhibition is considered as a useful therapeutic strategy for the treatment of a wide range of tumours." (PMID 23301673, 2013). "However, it does illustrate the need for greater understanding of PARP-1 involvement at active gene promoters, as well as the potential for manipulating PARP-1-mediated transcription to enhance efficacy of cancer therapy." (PMID 24350055, 2013). "In the context of certain cancers, PARP-1 interacts with the transcription factors HIF1 and Snail1." (PMID 23785295, 2013). "Furthermore, recent studies have shown that TMPRSS2:Erg and EWS-Fli1 fusion proteins also sensitise cancer cells to PARP-1 inhibitors by inducing DNA damage, although these studies did not investigate the accumulation of these proteins." (PMID 23405229, 2013). "Veliparib (ABT-888) is also a novel and potential anti-cancer drug acting as a PARP-1 inhibitor." (PMID 23451039, 2013). "This study represents a specific application of PARP-1-regulated NF-κB signaling to cancer therapy, one that may soon be expanded into a clinical trial." (PMID 24350055, 2013). "In conclusion, we provide evidence that Ets-1 may be a potential new candidate as a biomarker of cancer cell sensitivity to PARP-1 inhibition." (PMID 23405229, 2013). "While the mechanisms behind this are not yet determined, it does provide evidence that the applications of PARP-1 inhibitors in the treatment of cancers may be further extended than originally thought." (PMID 24202328, 2013). "This study did not meet the prespecified significance criteria for PFS and OS; ongoing molecular analyses of patients' tumor samples may identify cancer subtypes sensitive to PARP1 inhibition." (PMID 22645612, 2012). "Various cancers are known to display an overexpression of PARP1 and some may therefore be inherently more sensitive to PARP inhibition than non-malignant cells." (PMID 24970153, 2012). "Because PARP-1 also regulates angiogenesis, the effect of PARP-1 proteolysis by MMPs during angiogenesis may be important to investigate for cancer and chronic inflammation therapy." (PMID 21176168, 2010). "Poly(ADP-ribose) polymerase-1 (PARP-1) is an important novel target in cancer therapy." (PMID 20049345, 2010). "PARP-1 expression levels vary in carcinomas of different organs." (PMID 20196871, 2010). "Because ERK activity in the nucleus is a key modulator for inducing proliferation versus differentiation in a variety of cancer cells, these findings suggest that PARP-1 activation might be a possible target for mechanisms inducing cell proliferation." (PMID 19891779, 2009).
cancer (continued). "Indeed, we cannot exclude the possibility that the lower PARP-1 protein and activity seen in the immortalised non-cancer HS-5 cells was merely due to the fact that this was also relatively slow growing cell line in our panel." (PMID 19568233, 2009). "This evidence implicates PARP-1 primarily in inflammatory processes leading to the development of immunological disorders, but these may also lead to promotion and development of cancer by NF-κB dependent or independent mechanisms." (PMID 19568233, 2009). "As chromosomal missegregation and centrosome amplification frequently occur in cancer cells, leading to the characteristic aneuploidy, PARP-1 may protect against carcinogenesis." (PMID 19568233, 2009). "Given that the regulation of the PARP1 gene hinges on its promoter, alterations in the transcription binding sites within this region may negatively affect its expression, thereby reducing protein abundance and contributing to the progression of cancer." (PMID 40833230, 2025). "The detailed characterization of interactions between PARP1, chemotherapeutic treatment, and chemoresistance is essential in order to guide the design of treatment strategies that are more effective, thus providing cancer patients with a better prognostic outlook." (PMID 39990651, 2025). "Therefore, combination therapy with the AMPK inhibitor and the alkylating agent that activates PARP-1 may be an effective treatment strategy against cancer." (PMID 41226559, 2025). "Additionally, this approach may have broader implications for treating other cancers with PARP1 involvement, highlighting the translational potential of this combination therapy in clinical settings." (PMID 40303286, 2025). "In addition, we confirmed the involvement of PARP1 in the control of cancer stemness." (PMID 40986050, 2025). "To further assess downstream PARP1 signaling, we measured the expression of hypoxia-inducible factor 1 (Hif1a) and vascular endothelial growth factor alpha (Vegfa), both of which are involved in hypoxic and pro-angiogenic responses and are often dysregulated in cancer." (PMID 40869324, 2025). "Pioneering studies in 2005 revealed that concurrent loss of both PARP1 activity and BRCA1/2-mediated homologous recombination (HR) resulted in catastrophic DNA damage and selective tumor cell death, which have fundamentally reshaped strategies for targeted cancer therapies." (PMID 41460301, 2025). "Thus, deregulation of transcription can sensitize cancer cells to PARPi, as we previously demonstrated for the Ets‐1 factor, which accumulates in cells and whose transcriptional activity is increased by the inhibition of PARP‐1." (PMID 39778077, 2025). "Furthermore, synthetic lethality in BRCA-mutated cancers depends mostly on PARP1, whereas PARP2 is not essential." (PMID 40521389, 2025). "Further investigation of how PARylated PARP1 orchestrates FUS phase separation will deepen our understanding of neurological diseases and cancers caused by mutations in these proteins and may provide the basis for the development of innovative technologies in cancer therapy." (PMID 39596510, 2024). "In addition, other mechanisms of PARPi resistance involve modifications of the drug target, i.e., PARP1 conformation change to avoid PARP1 trapping—a phenomenon mentioned previously caused by PARPi drugs, although at present this has only been reported in pre-clinical BRCA1 mutant cancer models." (PMID 39119040, 2024). "As the inhibition of DTYMK and PARP1 was found to be effective in in vitro and in vivo trials in numerous malignancies due to their important function in maintaining genome stability, we suggest that the application of pamiparib together with Ymu1 may be beneficial for UM patients." (PMID 39195238, 2024).